EIF2S3B (eukaryotic translation initiation factor 2 subunit gamma B)
Description:
Member of the eIF2 complex that functions in the early steps of protein synthesis by forming a ternary complex with GTP and initiator tRNA. This complex binds to a 40S ribosomal subunit, followed by mRNA binding to form the 43S pre-initiation complex (43S PIC). Junction of the 60S ribosomal subunit to form the 80S initiation complex is preceded by hydrolysis of the GTP bound to eIF2 and release of an eIF2-GDP binary complex. In order for eIF2 to recycle and catalyze another round of initiation, the GDP bound to eIF2 must exchange with GTP by way of a reaction catalyzed by eIF-2B (By similarity).
Synonyms: eIF-2gA; eIF2gA; eIF-2-gamma2; EIF2S3L
Tractability: PROTAC: ubiquitination databases record sites on it.
Gene: Protein-coding gene on chromosome 12 (10,505,602 to 10,523,135, forward strand). Ensembl gene ENSG00000180574.
Gene Ontology:
Molecular function: GTPase activity; translation initiation factor activity; tRNA binding; GTP binding
Biological process: formation of translation preinitiation complex
Cellular component: eukaryotic translation initiation factor 2 complex
Genetic constraint (gnomAD): Loss-of-function variants: 14 observed, 24.44 expected, observed/expected ratio (o/e) 0.57, 90% interval 0.38 to 0.9. The upper end of that interval is the gene's LOEUF score, 0.9, which puts it in group 3 of 6, group 1 being the genes least tolerant of losing a copy. Missense variants: 471 observed, 551.03 expected, observed/expected ratio (o/e) 0.85, 90% interval 0.79 to 0.92. Synonymous variants: 172 observed, 192.7 expected, observed/expected ratio (o/e) 0.89, 90% interval 0.79 to 1.01.
Homologues: Orthologues: mouse Eif2s3x (98% identical), guinea pig EIF2S3B (98% identical), rat Eif2s3y (97% identical), tropical clawed frog eif2s3 (96% identical), zebrafish eif2s3 (95% identical), chimpanzee EIF2S3B (92% identical), pig EIF2S3B (92% identical), rabbit EIF2S3B (91% identical), chimpanzee EIF2S3 (89% identical), Drosophila melanogaster eIF2gamma (81% identical), Caenorhabditis elegans eif-2gamma (72% identical), Drosophila melanogaster mEFTu2 (16% identical), and 1 more. Paralogues in human: EIF2S3 (99% identical), EEF1A1 (26% identical), EEF1A2 (25% identical), TUFM (19% identical), GSPT1 (19% identical), GSPT2 (19% identical), HBS1L (18% identical), EEFSEC (17% identical), MTIF2 (17% identical), GFM1 (16% identical), EFTUD2 (16% identical), EEF2 (16% identical), and 6 more.
Diseases named in the same sentence as EIF2S3B in open-access papers:
EIF2S3B is named in the same sentence as 3 diseases in open-access papers, as found by Europe PMC text mining. Sharing a sentence is not in itself a finding about the gene and the disease. The quoted sentences say what the papers report.
Hyperinsulinemia (1 paper, 2024). An increased concentration of insulin in the blood. "In contrast, we observed the additive effect of hyperinsulinemia and JAKi on the cell cycle-controlling genes CDKN2D/p19, EIF2S3B, GREM2, and YBX3." (PMID 39768214, 2024).
cancer (3 papers, 2012 to 2020). A tumor composed of atypical neoplastic, often pleomorphic cells that invade other tissues. "It is this uniquely human situation that could lead to activation of EIF2S3B during oncogenesis and cancer development and provide an explanation for the expression of C/T antigens in the tumors of both human sexes." (PMID 33330072, 2020). "The presence of two autosomal copies of EIF2S3B in humans leads to the hypothesis that aberrant activation of EIF2S3B during cancer development could result in the activation of spermatogenic pathways within cancer stem cells in both males and females." (PMID 33330072, 2020).
tumor (1 paper, 2020). "Since activation of spermatogenic pathways is dependent on the level of EIF2S3 expression aberrant activation of EIF2S3B during tumor-genesis and differentiation could regulate the expression of C/T antigen genes." (PMID 33330072, 2020).